MUC12 (mucin 12, cell surface associated)
Diseases named in the same sentence as MUC12 in open-access papers:
MUC12 is named in the same sentence as 46 diseases in open-access papers, as found by Europe PMC text mining. Sharing a sentence is not in itself a finding about the gene and the disease. The quoted sentences say what the papers report.
colorectal cancer (8 papers, 2013 to 2023). A primary or metastatic malignant neoplasm that affects the colon or rectum. "MUC12, for example, is highly mutated and carcinogenic in colorectal cancer and clear cell renal cell carcinoma and promotes tumor invasion." (PMID 37024829, 2023). "MUC12 is associated with Tn polyagglutination syndrome and colorectal cancer and previous GWAS have pointed out the effect of the genetic variants in MUC12 on hemoglobin levels and CARS2 on diastolic blood pressure." (PMID 34064523, 2021). "MUC12 expression was a novel independent prognostic variable in patients with stages II or III colorectal cancer." (PMID 33330027, 2020). "However, MUC12 was also downregulated in colorectal cancer tissues compared with normal colorectal mucosa." (PMID 29659199, 2018).
renal cell carcinoma (4 papers, 2023 to 2025). "The oncogenic role of MUC12 in renal cell carcinoma is related to the c-Jun/TGF-β signaling pathway." (PMID 40996224, 2025). "MUC12, also a member of the mucin family, is overexpressed in renal cell carcinoma and promotes tumor metastasis via c-Jun/TGF-β signaling." (PMID 37024829, 2023).
ulcerative colitis (4 papers, 2014 to 2025). An inflammatory bowel disease involving the mucosal surface of the large intestine and rectum. "MUC12, the member of mucins protein family, is important for intestinal integrity and related to Crohn’s disease (CD) and ulcerative colitis (UC)." (PMID 35783128, 2022). "Mucins including MUC4, MUC12 and MUC17 are important for intestinal integrity and have previously been associated with both ulcerative colitis (UC) and Crohn's disease (CD)." (PMID 24988487, 2014).
colon cancer (3 papers, 2013 to 2023). "Robust markers of metaplasia in our study included cathepsin E (CTSE), which has been associated with gastric and colon cancers and previously shown to be upregulated in patients with BAR and EAC, as well as the anion/bicarbonate channel CFTR and PDZ-domain-containing mucins MUC17, MUC3A, and MUC12." (PMID 34412659, 2021).
Crohn disease (3 papers, 2014 to 2022). A gastrointestinal disorder characterized by chronic inflammation involving all layers of the intestinal wall, noncaseating granulomas affecting the intestinal wall and regional lymph nodes, and transmural fibrosis. "MUC12 and MUC20 are involved in the epithelial cell protection, and the significant downregulation of MUC12 and MUC20 in the colon and ileum has been detected in patients with Crohn’s disease." (PMID 31624342, 2020).
non-small cell lung carcinoma (3 papers, 2014 to 2024). A group of at least three distinct histological types of lung cancer, including non-small cell squamous cell carcinoma, adenocarcinoma, and large cell carcinoma. "Differential regulation of MUC1 and MUC12 in the lung has also been associated with non-small-cell lung cancer." (PMID 38245732, 2024). "Among 23 co-occurred pairs which we detected in our current AA ESCC tumor samples, mutant MUC4 and MUC12 pairing is interesting as this pair was previously observed in smoking-associated non-small cell lung cancer patients." (PMID 34285259, 2021). "We correlated the mutation frequency of MUC4, MUC6, and MUC12 with the non-small-cell lung carcinoma, and identified a distinct mutation frequency in tumor samples from smokers (20%) and non-smokers (6%), which cumulatively designates these MUC genes as diagnostic and prognostic markers in smokers." (PMID 24947164, 2014). "Analysis of 591 lung carcinoma tumor exomes from The Cancer Genome Atlas (TCGA) revealed that 20% of non-small-cell lung cancer tumors in smokers have mutations in at least one of the MUC4, MUC6 or MUC12 genes in contrast to only 6% in non-smokers." (PMID 24947164, 2014).
lung carcinoma (2 papers, 2014 to 2022). "Mutations in MUC12 have been observed at higher frequencies in the samples of familial lung cancer samples and lung cancer tissue, compared with those in the healthy population." (PMID 36059804, 2022). "To identify a possible association of MUC4, MUC6, and MUC12 with lung cancer, we analyzed the publicly available The Cancer Genome Atlas (TCGA) exome sequence data for lung adenocarcinoma and lung squamous cell carcinoma." (PMID 24947164, 2014).
renal carcinoma (2 papers, 2022 to 2023). A carcinoma arising from the epithelium of the renal parenchyma or the renal pelvis. "Investigations on sunitinib-based targeted therapies have offered convincing evidence for the substantial contributions of MUC12 to renal cancer occurrence and indicate that MUC12 is a critical metastatic promoter of the RCC phenotype." (PMID 37332045, 2023). "We also found by western blotting that MUC12 was highly expressed in renal cancer tissues." (PMID 37332045, 2023). "For example, TGF-β1 enhances the proliferation and metastatic potential of RCC cells by upregulating lymphoid enhancer-binding factor 1/integrin αMβ2, and MUC12 relies on TGF-β1 signaling to mediate the growth and invasion of renal cancer cells." (PMID 36186427, 2022).
adenoma (1 paper, 2022). A neoplasm arising from the epithelium. "At baseline, obesity, history of a sessile-serrated adenoma, and a family history of CRC were associated with claudin-1, occludin, and mucin-12 (MUC12)." (PMID 35406694, 2022).
autoimmune disease (1 paper, 2021). A disorder resulting from loss of function or tissue destruction of an organ or multiple organs, arising from humoral or cellular immune responses of the individual to their own tissue constituents. "According to the literature, MUC family genes (such as MUC12) carry a lot of mutations in autoimmune diseases." (PMID 34723755, 2021).
breast carcinoma (1 paper, 2017). "Lastly, despite many cancers observed not to harbor mutations in MUC12 and MUC19, breast cancer appears to have a unique profile." (PMID 28978023, 2017).
cholesteatoma (1 paper, 2023). A pathologic process characterized by the proliferation of keratinizing squamous epithelium resulting in the accumulation of keratin and cells in the middle ear and/or mastoid. "However, whether TIAL1 and MUC12 are involved in the pathogenesis of cholesteatoma requires further investigation." (PMID 37609036, 2023).
cystic fibrosis (1 paper, 2023). Autosomal recessive disorder caused by pathogenic variants in the CFTR gene (cystic fibrosis transmembrane conductance regulator), which encodes a chloride and bicarbonate channel expressed in epithelial cells, and follow the diagnosis criteria. "MUC12 extracellular domains are frequently shed in overabundance in cystic fibrosis, inflammatory bowel disease, and metastatic carcinomas." (PMID 37332045, 2023).
desmoid tumor (1 paper, 2022). A desmoid tumor (DT) is a benign, locally invasive soft tissue tumor associated with a high recurrence rate but with no metastatic potential. "Besides the well-known CTNNB1, which was identified 100% mutation in our samples, we also identified several mutations, such as membrane-associated mucins (MUC4, MUC12), which may also play some role in the development and progression of pediatric desmoid tumors." (PMID 36539683, 2022).
esophageal cancer (1 paper, 2023). A primary or metastatic malignant neoplasm involving the esophagus. "In summary, these data indicate correlation between the proproliferation and antiapoptotic effects of MUC13 with the expression of GLANT14, MUC3A, MUC1, MUC12 and MUC4 in esophageal cancer." (PMID 37395858, 2023). "In this study, we confirmed that GLANT14, MUC3A, MUC1, MUC12, and MUC4 regulatory factors which related to the O-glycan process were overexpressed and downregulated with MUC13 knockdown in esophageal cancer cells, resulting in insufficient tumor growth and proliferation." (PMID 37395858, 2023).
lung disorder (1 paper, 2019). A disease involving the lung. "Another notable result was the presence in the list of various mucin-encoding genes (MUC5B, MUC12, and MUC16), which are commonly observed mutated in many cancers and have been previously linked to colorectal, ovarian and hepatological cancers, as well as to severe fibrotic lung disorders." (PMID 31156702, 2019).
ovarian carcinoma (1 paper, 2023). A malignant neoplasm originating from the surface ovarian epithelium. "The tumor specificity of MUC12 and FLG is not strong, and the early diagnosis of MUC16 in ovarian cancer is not satisfactory." (PMID 37024829, 2023).
schizophrenia (1 paper, 2025). A major psychotic disorder characterized by abnormalities in the perception or expression of reality. "Analysis of the top 10 genes containing the most differential polymorphisms specifies such genes related to schizophrenia as MUC12 and SH3KBP1." (PMID 40416497, 2025). "In the study, the MUC12 gene was included in the top 10 mutated genes in the research of early schizophrenia (childhood-onset schizophrenia)." (PMID 40416497, 2025).
uterine corpus endometrial carcinoma (1 paper, 2017). A endometrial carcinoma (disease) that involves the body of uterus. "Despite the low mutation rate, this suggests a possible connection between MUC12 and BRCA, as the mutations appear low in most tissues except for BRCA and uterine corpus endometrial carcinoma (UCEC)." (PMID 28978023, 2017).
tumor (20 papers, 2012 to 2025). "GSEA based on the KEGG database showed that MUC12 expression was closely associated with pathways related to tumor development and progression, such as angiogenesis." (PMID 37332045, 2023). "In contrast, the HPV-positive tumor had five mutations in four different mucin genes, including the secreted Muc6, and the transmembrane bound Muc4, Muc12 and Muc16." (PMID 23304554, 2012). "Immunofluorescence and IHC staining of subcutaneous tumor tissues showed that treatment with pPM-NPs in combination with sunitinib significantly inhibited the expression of MUC12." (PMID 37332045, 2023). "In this research, the MUC12 expression level was shown to be elevated in larger xenograft tumor samples, whereas the expression of MUC12 was inhibited when piR-1742 was knocked down." (PMID 37332045, 2023). "As a consequence of these findings, it was postulated that piR-1742/USP8/MUC12 played a significant role in the regulation of MUC12-mediated tumor invasiveness via a ‘one-hit/multiple targets’ process." (PMID 37332045, 2023). "Upon multivariate analysis, tumor MUC12 expression levels were found to be an independent prognostic factor." (PMID 36900282, 2023). "MUC12 expression was markedly positively linked to cell death, IFN-γ, and the tumor microenvironment but significantly negatively correlated with the growth and differentiation of normal kidneys." (PMID 37332045, 2023). "TCGA database analysis suggested that high expression of MUC12 was closely related to high tumor grade and metastasis." (PMID 37332045, 2023). "Subsequently, we analyzed the expression of MUC12 in the TCGA database and found that MUC12 was highly expressed in tumor tissues and that MUC12 expression correlated with T-stage, N-stage, M-stage, histological grade and pathological stage." (PMID 35986402, 2022). "We examined the expression of MUC12 in different tumor types and found that its expression was upregulated in RCC in the TCGA database and that high expression of MUC12 was an independent risk factor for OS and DFS in RCC patients." (PMID 35986402, 2022). "MUC12 is one of the most strongly expressed tumor surface antigens that promotes epithelial cell protection, adhesion modulation, and cell growth regulation signaling." (PMID 35986402, 2022). "In vitro experimental results also confirmed that MUC12 served as tumour‐promoting factor to increase RCC cell growth and cell invasion." (PMID 32596961, 2020). "Together, these results indicate that MUC12 acts as a tumour supporting factor to promote RCC cell growth." (PMID 32596961, 2020). "In summary, our data identify MUC12 as a tumour promoting factor in advanced RCC by activating TGF‐β1 signalling and provide compelling rational to develop MUC12‐targeted therapies for RCC patients." (PMID 32596961, 2020). "Only a single genetic mutation (Muc12) was shared by both HPV-positive and HPV-negative tumor samples." (PMID 23304554, 2012). "The experimental results showed that overexpression of MUC12 significantly promoted tumor growth." (PMID 37332045, 2023). "However, injection of the piR-1742 antagomir into subcutaneous tumors overexpressing MUC12 inhibited tumor growth." (PMID 37332045, 2023). "In addition, IHC staining showed that MUC12 expression was increased in tumor as well as metastatic samples, and MUC12 expression increased with increasing tumor stage." (PMID 35986402, 2022). "Importantly, the observed identical MFI2, MUC12, UBE2H, and TBX2 mutations were each observed in a patient-matched tumor pair and an additional tumor sample." (PMID 32604718, 2020). "Importantly, MUC12 expression levels were also strongly correlated with clinical stage, pathological grade, tumour recurrence and tumour metastasis, showing that higher MUC12 levels were observed in more advanced RCC patients." (PMID 32596961, 2020). "Besides, the linear curve also recorded that knocking down MUC12 dramatically suppressed the average weight of tumours in nude mice." (PMID 32596961, 2020).
tumor (continued). "Moreover, elevated expression of MUC12 in RCC was found to be considerably linked to higher TNM stage, larger tumor size, and unfavorable prognosis, confirming the finding that piR-1742 overexpression is correlated with higher TNM stage and larger tumor size." (PMID 37332045, 2023). "Together, all these data indicate that MUC12 may serve as tumour‐promoting factor in RCC patients." (PMID 32596961, 2020). "MUC12 belongs to the mucin (MUC) family, and we have intensively investigated the role of the Mucin family in tumor progression." (PMID 37332045, 2023). "In contrast, MUC12 was considerably related to unsatisfactory OS in LUAD patients with a smoking history, stage I or II tumours, and being female." (PMID 36059804, 2022). "The Plasmid-SLERCC@PDA@MUC12 nanoparticles (PSPM-NPs) were tested in vivo and in vitro, including cellular uptake, entry, CCK-8 assay, tumor growth inhibition, histological assessment, and safety evaluations." (PMID 35986402, 2022). "Specifically, three membrane‐bound MUCINs (MUC3A, MUC12, and MUC20) and one atypical mucin (MCAM) were overexpressed in the tumor samples (p < 0.05)." (PMID 34327857, 2021). "Previous studies have found that the expression levels of MUCINs, including MUC1, MUC4, MUC12, MUC13, MCAM, and LAMA4 were correlated with poor survival of ccRCC patients, and/or promotion of tumor cell proliferation in vitro." (PMID 34327857, 2021). "Consistent with the bioinformatics predictions, MUC12 and NXPE1 presented a sequentially descending trend in expression with tumor progression, and TIMP1 presented a sequentially ascending trend." (PMID 29659199, 2018). "HEPACAM2, ITLN1, LGALS2, MUC12, and NXPE1 presented a sequentially descending trend in expression with tumor progression." (PMID 29659199, 2018). "Most of these genes (MUC12, S100P, GSTT1, USP9Y, MSLN and so on) are involved in tumor initiation, progression or metastasis." (PMID 23787019, 2013). "Moreover, the highest SNVs variance was observed in AHNAK2, AHNAK, MUC12, and KMT2C across the Patient 1 tumor, UW-CSCC1 and UW-CSCC1-R." (PMID 33333825, 2020). "In early stages, MUC12 may play a protective role by maintaining epithelial barrier function, while its overexpression may contribute to EMT and microenvironmental remodeling, promoting tumor cell metastasis and invasion during tumor progression." (PMID 40613523, 2025).
cancer (17 papers, 2011 to 2025). A tumor composed of atypical neoplastic, often pleomorphic cells that invade other tissues. "The genes of the MUC family, which includes MUC3 and MUC12, code for transmembrane mucins, and are involved in epithelial cell protection, adhesion modulation, and signalling; their aberrant expression could be associated with human cancers." (PMID 21957467, 2011). "Although many other cancer-related genes showed a high frequency of mutations in OS, the MUC family of genes (MUC6, MUC12, and MUC4) were found to be highly mutated in our study." (PMID 37046795, 2023). "As for MUC12, it is a member of the mucin family and participates in cancer progression, owing to its capacity to transduce intracellular signaling." (PMID 37609036, 2023). "Result exhibited that the activation of TGF‐β1 signalling, a central signalling involved in cancer growth and migration, was observed in MUC12 high group." (PMID 32596961, 2020). "In this study, we found that MUC12 was overexpressed in RCC patients compared to normal kidney tissues and its levels were gradually increased as this type of cancer progressed to later stage according to TCGA data set." (PMID 32596961, 2020). "MUC12 was the next most significantly disrupted gene with no cancer classification, ranking 20th overall." (PMID 39441719, 2024). "Only two signatures (MUC12 and RYR2) predicted prognosis in ER-negative/HER2-negative cancers." (PMID 29559730, 2018). "Interestingly, albeit previous studies have argued that some of the MUCs should be excluded as cancer genes based on biological relevance, there is much evidence supporting the link between MUC12 and MUC16 and cancer development and evolution." (PMID 31156702, 2019). "However, MUC12, MUC15, MUC17, and MUC20 had a significant increase in methylation in only KIRP and KIRC, which goes against the overall observed demethylation of mucins in the cancers examined here." (PMID 28978023, 2017). "For MUC12, MUC17, MUC20 and MUC22, no statistical differences between cancer samples and normal controls were observed." (PMID 34828282, 2021).
infection (5 papers, 2022 to 2025). The state of being infected such as from the introduction of a foreign agent such as serum, vaccine, antigenic substance or organism. "For instance, the membrane-tethered MUC12 exhibited a similar expression pattern to MUC19 after EBV primary infection." (PMID 40996224, 2025). "In contrast, G5P infection decreased expression of transmembrane mucin genes significantly (MUC12, MUC16 and MUC21) or numerically (MUC1, MUC4, MUC13 and MUC20)." (PMID 37848925, 2023). "Following infection with SARS-CoV-2, multiple mucin genes showed significantly positive correlations in the digestive tissues, particularly MUC1, MUC12 and MUC13." (PMID 38563680, 2024).
MUC12 also shares sentences with these, for which no sentence is quoted: pancreatic cancer (2 papers); autosomal dominant tubulointerstitial kidney disease (1); clear cell renal cell carcinoma (1); colorectal adenoma (1); glioma (1); head and neck cancer (1); head and neck squamous cell carcinoma (1); hepatocellular carcinoma (1); hyperuricaemia (1); inflammation (1); inflammatory bowel disease (1); kidney disease (1); leiomyoma (1); lung adenocarcinoma (1); lung squamous cell carcinoma (1); meningioma (1); metastatic carcinoma (1); mucinous colorectal adenocarcinoma (1); Obesity (1); ovarian clear cell cancer (1); prostate carcinoma (1); systemic inflammatory response syndrome (1); type 1 diabetes (1); virus infection (1).